TGFB1 (transforming growth factor beta 1)
Diseases named in the same sentence as TGFB1 in open-access papers (continued):
Sharing a sentence is not in itself a finding about the gene and the disease.
cervical carcinoma (209 papers, 2007 to 2026). A carcinoma arising from either the exocervical squamous epithelium or the endocervical glandular epithelium. "Later, down regulation of SMAD4, which affected the metastatic potentials in early stages of cervical cancer, was associated with TGFB1 down regulation and incriminated cervical cancer." (PMID 26308848, 2015). "Furthermore, TNFRSF12A (TWEAK-R), NT5E (CD73), and TGFB1/TGFBR1 were genes where low expression was significantly associated with increased survival in both cervical cancer and HNSCC, demonstrating that high expression of these immune genes is detrimental to outcome." (PMID 36575316, 2023). "The hazard ratio values of TGFB1 and TGFBR1 were both > 1, indicating these as high-risk genes in cervical cancer." (PMID 39312339, 2024). "Results showed that relatively low TGF-β and high PGE2 (low TGFB1/COX2 gene ratio) was correlated with better overall survival in cervical cancer cohorts compared with high TGF-β and low PGE2 (high TGFB1/COX2 gene ratio)." (PMID 38164187, 2024). "They showed that the TGFB1 T10C and XRCC1 G399A polymorphisms were associated with cervical cancer risk." (PMID 34837895, 2021). "We then questioned the possibility of a link between the METTL3/TGFβ1/Snail axis and the clinical development of cervical cancer." (PMID 31991845, 2020). "In line with this, expression of TGFB1 was found to be downregulated in cervical precancerous lesions compared to normal epithelium although it is increased in cervical cancers." (PMID 32188026, 2020). "Using the online bioinformatics tool Kaplan–Meier plotter, we found that cervical cancer patients with increased expression of TGFB1 showed reduced overall survival (OS)." (PMID 31991845, 2020). "TGFB1 expression in cervical cancer tissues was significantly (p < 0.01) greater than that in normal tissues, according to TCGA Cervix and Scotto Cervix data from the Oncomine database." (PMID 31991845, 2020). "By analyzing clinical data of cervical cancer, the correlation between METTL3 and TGFβ1 was relatively weak, which was mainly due to the inclusion of primary cervical cancer cases." (PMID 31991845, 2020). "TGFB1 and TGFBR1 are known as high-risk factors for cervical cancer." (PMID 39312339, 2024). "Specifically, TGFB1, WNT3A, and their targets are the top signaling pathway inhibited in immunotherapy responded cervical cancer." (PMID 34921236, 2021). "This gene is overexpressed in cervical cancer, and its expression positively correlates with HPV load, and also PD-L1 and TGFB1 expression." (PMID 28670312, 2017). "The ENO1 regulator gene, which we found to be overexpressed in cervical cancer, positively correlated with PD-L1 (CD274) and TGFB1 in both data sets, providing further indication for immunotherapy targeting in this malignancy." (PMID 28670312, 2017). "Furthermore, the mRNA expression of TGFB1 was negatively correlated with the expression of METTL3, while positively correlated with the expression of SNAI1 in 169 cases of cervical cancer patients." (PMID 31991845, 2020).
Autoimmunity (199 papers, 2009 to 2025). The occurrence of an immune reaction against the organism's own cells or tissues. "Dysregulation of Tgfβ1 signaling has been implicated in various autoimmune disorders, highlighting its crucial role in maintaining immune homeostasis and preventing autoimmunity." (PMID 38975343, 2024). "Dysfunction of TGFβ1-mediated T cell balance is associated with autoimmune disorders and thus molecular principles of TGFβ-regulation of T cell activities are of important medical interest." (PMID 25482031, 2014). "Therefore, inhibition of TGFβ signaling in T cells causes autoimmunity similar to that in Treg-deficient mice and TGFβ1 deficiency in humans causes severe inflammatory bowel disease and encephalopathy." (PMID 35990633, 2022). "The isoform of TGFβ could also impact Th17 cells as TGFβ3 is more efficient than TGFβ1 in the induction of pathogenic Th17 cells leading to autoimmunity." (PMID 36016413, 2022). "Tgfb1, the gene encoding TGF-β is another important mediator of the suppressive activity of Tregs that limits autoimmunity." (PMID 36684560, 2022). "TGFB1 haploinsufficiency in Tregs leads to food allergies while biallelic TGFB1 deletion results in autoimmunity, consisting of autoantibody release and dysregulations in DCs and effector T cells." (PMID 34512655, 2021). "TGFβ1 has been described to be anti-inflammatory, inducing immune tolerance in the periphery and preventing autoimmunity." (PMID 34776983, 2021). "Our data further strengthen the rationale to develop RA+TGFβ1-based micro/nanoparticle “vaccines” as possible treatments of pre-symptomatic and new-onset T1D autoimmunity." (PMID 33763059, 2021). "TGFβ-1 and IL-10 cytokines have a central role in maintaining the immune balance by limiting immune reactions and promoting additional inducible regulatory T cell differentiation (iTreg), thus preventing uncontrolled inflammation and/or autoimmunity." (PMID 34071714, 2021). "It has been recently reported that TGFβ1 production by resting human B cells is negatively controlled by activation and it may contribute to excessive immune responses and autoimmunity." (PMID 30544541, 2018). "Additionally, because of the critical immunosuppressive role of TGFβ1, pan-TGFβ blockade can lead to excessive autoimmunity and inflammation, which could be highly deleterious in a fibrotic organ with limited functional reserve." (PMID 27139180, 2016). "The immunological role of TGFβ1 includes broad anti-inflammatory and immunosuppressive effects, and the complete knockout of TGF-β1 in mice results in autoimmunity and early death from a multi-organ inflammatory syndrome." (PMID 36671458, 2022). "The pharmacological blockade of αv‐containing integrins by cilengitide inhibits TGFβ1 signalling and produces the desired antifibrotic effects without the potential side effects of blocking pan‐TGFβ1, such as autoimmunity and carcinogenesis." (PMID 38239077, 2024). "Similarly, transforming growth factor (TGF)β1 non-responsive mice and TGFβ1-null mice do not survive severe widespread autoimmunity, which also involves the intestine." (PMID 40227443, 2025). "Thus, LPS-activated B cells express high levels of TGFβ1 and their transfer into prediabetic NOD (non-obese diabetic) mice inhibits spontaneous Th1 immunity and disease progression by down-regulating T cell autoimmunity or by modulating the function of APCs (Antigen Presenting Cell)." (PMID 30544541, 2018).
Cirrhosis (197 papers, 1997 to 2026). A chronic disorder of the liver in which liver tissue becomes scarred and is partially replaced by regenerative nodules and fibrotic tissue resulting in loss of liver function. "In our study, the amelioration of cirrhosis-associated immune dysfunction by propranolol treatment was accompanied by a decrease in the frequency of Treg cells and corresponding TGFβ1, IL-10 and IL-35 levels in circulation and in the spleen." (PMID 32138352, 2020). "HDV coinfection or superinfection into individuals with chronic HBV causes dramatic worsening of cirrhosis and inflammation, based in part on HDAg induction of TGFB1 (encoding the secreted factor TGFβ) and the cell cycle-promoting transcription factor JUN." (PMID 29945886, 2018). "Our past research indicated that TGFB1 polymorphisms could influence hepatitis patients' inflammation levels, a finding supported by a recent meta‐analysis showing the significant impact of TGFB1 polymorphisms on the incidence of cirrhosis among individuals with HCV." (PMID 38970443, 2024). "The rNK cells in NASH cirrhosis expressed higher levels of TGFB1 and demonstrated inhibition of the HSC apoptosis pathway." (PMID 37063898, 2023). "Consistent with these experimental findings, immunohistochemical assessment of splenic tissues in patients with cirrhosis reveals increased content of TGFβ1 and its colocalization with CD68+ cells (macrophages)." (PMID 35629294, 2022). "In a rat model of thioacetamide-induced cirrhosis, splenectomy leads to a decrease in blood levels of TGFβ1, considered beneficial for reparative processes in the damaged liver." (PMID 35629294, 2022). "The elevated levels of pro-fibrotic TGFβ1, characteristic of hepatitis eventually resolved in cirrhosis, may significantly depend on the increased production of this factor by activated macrophages of the splenic red pulp." (PMID 35629294, 2022). "Decorin was found to be produced by HSCs under TGFβ1 stimulus and appears histologically coexpressed and colocalized with this cytokine in a spectrum of liver diseases, including chronic hepatitis, fibrosis, and cirrhosis." (PMID 35454809, 2022). "However, in the present study's ESM group, Tgfβ3, not Tgfβ1, was differentially down-regulated, the relevance of which is supported by our previous finding that the expression of Tgfβ3 was 2.6-fold higher than the Tgfβ1 expression in a CCl4-induced rat cirrhosis model for 19 wks2." (PMID 25503635, 2014). "Interestingly, genes associated with early cell cycle control (G1/S) and apoptosis in liver cells (TGFβ1, EGFR) were found downregulated in HCV-cirrhosis with HCC." (PMID 22792259, 2012). "We found them to be upregulated in cirrhosis represented by the upregulation of PGDFRB, TGFB1 (TGF‐β1), TGFB1I1 (TGF‐β1 induced transcript 1 protein), TGFBI (TGF‐β induced protein ig‐h3), LTBP1, LTBP2, LTBP4, and ENG (transmembrane accessory receptor for TGF‐beta signaling)." (PMID 35579278, 2022). "Many studies have shown that an increase in transforming growth factor beta 1 (TGF-β1) in hepatic tissue and serum, activates hepatic stellate cells (HSC), a major source of extracellular matrix (ECM), whose altered deposition can increase fibrosis and hence cirrhosis." (PMID 33072455, 2020).
systemic sclerosis (194 papers, 2009 to 2026). A chronic disorder, possibly autoimmune, marked by excessive production of collagen which results in hardening and thickening of body tissues. "For example, in fibroblasts derived from patients with systemic sclerosis, IRE1α was required for TGFβ1-induced differentiation into activated myofibroblasts." (PMID 30625178, 2019). "TGFB1 is recognized to play a major pathophysiological role in systemic sclerosis, a chronic inflammatory and autoimmune disorder affecting the connective tissue." (PMID 31779094, 2019). "In clinical trials, a TGFβ1 inhibitor and a monoclonal antibody against TGFβ1 were found to be ineffective in the treatment of scleroderma and systemic sclerosis, and human recombinant TGFβ3 failed in a phase III clinical trial on human scarring." (PMID 31231509, 2019). "A previous study has shown that TGFβ1 may lead to the reduction of miR-29a levels in fibroblasts in patients with systemic sclerosis." (PMID 39023839, 2024). "A topical application of a peptide inhibitor of TGFβ1 (P144) in a mouse model of systemic sclerosis revealed the remarkable suppression of connective tissue growth factor expression in fibroblast SMAD2/3 phosphorylation, and α-smooth muscle actin positive myofibroblast development." (PMID 37630981, 2023). "We evaluated PDGFA, TGFB1, TGFB2, and TGFB3 role in the diagnosis of ILD associated with rheumatoid arthritis (RA), systemic sclerosis (SSc), and inflammatory myopathies (IM)." (PMID 41226758, 2025). "In patients suffering from systemic sclerosis, the anti-TGFB monoclonal antibody fresolimumab, which targets the 3 TGFB isoforms (TGFB1, TGFB2, and TGFB3), was shown to be well tolerated and clinically efficient in a phase II clinical trial." (PMID 31779094, 2019). "Furthermore, inhibition of STAT3 in fibroblasts showed reductions in TGFβ1-induced FMT and alleviated skin fibrosis in mouse models of systemic sclerosis." (PMID 37833957, 2023). "Further, STAT3 regulates IL-6–mediated and TGF-β1–mediated myofibroblast differentiation in murine lung fibroblasts, and inhibition of STAT3 was found to reduce TGFβ1-induced FMT in fibroblasts, and ameliorate skin fibrosis in two mouse models of systemic sclerosis." (PMID 34207510, 2021).
Marfan syndrome (188 papers, 2007 to 2026). A disorder of the connective tissue. "Mutations in fibrillin-1 cause the connective tissue disease Marfan syndrome and influence the bioavailability of TGFβ1." (PMID 36523505, 2022). "Recently, high plasma TGFβ1 levels have been implicated in the manifestation of aortic root dilation in Marfan syndrome." (PMID 22607024, 2012). "In contrast to being upregulated after TGFβ-1 (10 ng / mL) treatment, the ligand-receptor pair fibrillin 1 (fbn1) - integrin alpha-V (Itgav) was significantly downregulated after ALKi treatment: Fbn1 mutations are the main cause for Marfan Syndrome." (PMID 36193159, 2022). "For example, people with Loewy’s-Dietz syndrome caused by increased signaling through the TGFβ1 receptor have higher rates of food allergy and connective tissue disorders such as Marfan’s syndrome in which there is also increase TGFβ1 signaling, associates with EoE." (PMID 26656423, 2015). "Mice with a mutation in fibrilin-1 analogous to that found in humans with Marfan syndrome, display chronically increased TGFβ1 signaling, which impairs muscle regeneration by inhibiting MuSC proliferation and differentiation." (PMID 36523505, 2022). "Variants in TGFB1/2 have been identified in several syndromic causes of thoracic aortic aneurysm and dissection (TAAD), including Marfan syndrome (MFS), Loeys–Dietz syndrome (LDS), and Shprintzen–Goldberg syndrome (SGS)." (PMID 38892036, 2024).
breast tumor (187 papers, 1991 to 2026). "With regard to clinical relevance, we identified a pS134-GR 24-gene signature induced by TGFβ1 that may serve as a valuable paired diagnostic with which to identify patients who have GR-driven breast tumors and are thus at high risk of succumbing to metastatic disease." (PMID 32357907, 2020). "However, alleles in this region associated with increased TGFB1 levels may reduce the risk of estrogen receptorpositive breast tumors." (PMID 17848193, 2007). "In contrast to these previous findings, we find that TGFβ1 treatment significantly decreases the levels of G9a in mammary epithelial cells cultured on stiff hydrogels that mimic the mechanical properties of breast tumors." (PMID 40661662, 2025). "Our results showed that the spots of FIB-INMON interactions with co-expression of ANXA1-FPR3 and TGFB1-TGFBR1/2 in the breast tumor sample are close to the C9 but distant to the C4 population." (PMID 38645221, 2024). "Of note, as a consequence of the joint activities of TNFα + TGFβ1 stimulation, the MSCs released factors that have led to elevated migratory and scattering processes in breast tumor cells." (PMID 28553282, 2017). "As expected, in our series, lower levels of both BRCA1 and ATM genes were observed in sporadic breast tumors in which higher expression of TGFB1 was observed." (PMID 28881597, 2017). "Along these lines, in recent preliminary studies, we have generated mRNA expression profiles of breast tumor cells grown in the presence of CM derived from TNFα + TGFβ1-stimulated MSCs." (PMID 28553282, 2017). "To this end, we determined the effects of factors that were secreted by MSCs—following their activation by TNFα + TGFβ1 together—on characteristics of breast tumor cells that are connected to increased motility and spreading." (PMID 28553282, 2017). "Studies with MSCs activated by TNFα + TGFβ1 revealed that they release factors that can affect other cells in their microenvironment and induce breast tumor cell elongation, migration, and scattering out of spheroid tumor masses." (PMID 28553282, 2017). "A cascade-type of interaction was found in adipose tissue-derived MSCs, which upon priming with TNFα released TGFβ1 that, in turn, elevated the malignancy phenotype of breast tumor cells." (PMID 28553282, 2017). "For example, upon binding with HA, CD44 interacts with TGFβ receptor I, resulting in the activation of TGFβ1 signaling in metastatic breast tumor cells." (PMID 28002484, 2016). "TGFβ1 treatment induced the phosphorylation of Smad2/3, which in turn, led to upregulation of miR-21 in both breast tumor cell lines; whereas SSA reduced miR-21 expression through inhibition of Smad2/3 phosphorylation." (PMID 26769851, 2016). "TGFβ1 has been shown to be overexpressed in human breast tumor and its expression level correlates with metastasis of breast cancer." (PMID 27641158, 2016). "In our present work we found a definitive poor outcome in patients whose primary breast tumors showed higher expression of cytoplasmic TGFβ1." (PMID 26040677, 2015). "In this study, we have measured for the first time the level of TGFβ1 protein in breast tumour samples by ELISA, in order to examine potent correlations with clinical features." (PMID 16404434, 2006). "Recently, single-cell analysis of human breast tumours identified a cluster of FAP+ fibroblasts whereby subpopulations enriched in ECM proteins and TGFβ1 signalling were linked with regulation of host immune response via upregulation of PD-1 and CTLA4 expression on Tregs." (PMID 34740105, 2021). "Furthermore, sporadic BCs showed a higher percentage of TGFB1 over-expression compared to familial breast tumors (60 vs 42.1 %; p=0.44)." (PMID 28881597, 2017). "Following stimulation of the MSCs for 24 h by TNFα + TGFβ1 or by their vehicles, the CM of cytokine-stimulated or of vehicle-exposed cells (Groups 4 and 3, respectively) were transferred to mCherry-expressing breast tumor cells." (PMID 28553282, 2017).